COX11 (cytochrome c oxidase copper chaperone COX11)
Description:
Assembly factor for cytochrome c oxidase (respiratory chain complex IV, CIV). Probably acts as a metallochaperone that delivers copper to the copper B site of COX1.
Synonyms: COX11P; MC4DN23
Tractability: Antibody: UniProt predicts a signal peptide or a membrane-spanning region. PROTAC: ubiquitination databases record sites on it; its protein half-life has been measured.
Gene: Protein-coding gene on chromosome 17 (54,951,902 to 54,968,703, reverse strand). Ensembl gene ENSG00000166260.
Subcellular location: Mitochondrion inner membrane
Pathways (Reactome):
Metabolism: Complex IV assembly
Gene Ontology:
Molecular function: protein binding; copper chaperone activity; copper ion binding
Biological process: ATP biosynthetic process; intracellular monoatomic cation homeostasis; mitochondrial respiratory chain complex IV assembly
Cellular component: mitochondrial inner membrane; mitochondrion; protein-containing complex
Genetic constraint (gnomAD): Loss-of-function variants: 14 observed, 27.7 expected, observed/expected ratio (o/e) 0.51, 90% interval 0.33 to 0.79. The upper end of that interval is the gene's LOEUF score, 0.79, which puts it in group 3 of 6, group 1 being the genes least tolerant of losing a copy. Missense variants: 311 observed, 365.07 expected, observed/expected ratio (o/e) 0.85, 90% interval 0.78 to 0.94. Synonymous variants: 131 observed, 132.36 expected, observed/expected ratio (o/e) 0.99, 90% interval 0.86 to 1.14.
Gene-disease validity (ClinGen):
ClinGen rates the evidence that COX11 causes each of these diseases.
mitochondrial disease (autosomal recessive): Limited.
Homologues: Orthologues: chimpanzee COX11 (99% identical), macaque COX11 (92% identical), pig COX11 (86% identical), rabbit COX11 (85% identical), rat Cox11 (84% identical), mouse Cox11 (83% identical), guinea pig COX11 (82% identical), dog COX11 (79% identical), zebrafish cox11 (57% identical), Drosophila melanogaster Cox11 (46% identical), tropical clawed frog cox11 (44% identical), Caenorhabditis elegans cox-11 (38% identical). Paralogues in human: METTL17 (20% identical).
Diseases named in the same sentence as COX11 in open-access papers:
COX11 is named in the same sentence as 22 diseases in open-access papers, as found by Europe PMC text mining. Sharing a sentence is not in itself a finding about the gene and the disease. The quoted sentences say what the papers report.
breast carcinoma (6 papers, 2010 to 2024). "Data analysis of STXBP4/COX11 polymorphisms and breast cancer risk showed that alleles of COX11 (rs17817901, rs6504950) were positively associated with breast cancer risk." (PMID 39676279, 2024). "In the normal tissue samples (n=135) from the METABRIC study the top breast cancer candidate causal variant was also associated with COX11 expression levels." (PMID 27600471, 2016). "We identified 13 members of the copper transport system associated with the occurrence, progression, and mortality of breast cancer, including SLC31A1, DMT1, ATP7A, ATP7B, MTs, GSH, ATOX1, CCS, COX17, SCO1, SCO2, and COX11." (PMID 39676279, 2024). "This is also supported by the increased expression of SLC31A1, SCO1, and COX11 mRNA observed in cell lines with a different tissue origin, such as MCF7 (breast cancer) and PC3 (prostate cancer)." (PMID 27516958, 2016). "Of the candidate genes in the region, both COX11 and TOM1L1 are highly expressed in both the HMEC and MCF7 breast cancer cell lines, while STXBP4 shows much lower expression (detected by RNAseq in TCGA)." (PMID 27600471, 2016). "Comparing the ORs for male breast cancer with the published ORs for female breast cancer, three SNPs—rs13387042 (2q35), rs3803662 (TOX3), and rs6504950 (COX11)—showed significant differences in ORs (p<0.05) between sexes." (PMID 21949660, 2011). "eQTL analysis in breast tumour tissues in TCGA find the risk allele of top candidate breast cancer risk SNP, rs2787486, to be significantly associated with increased STXBP4 expression, but not with COX11." (PMID 27600471, 2016).
gastric cancer (3 papers, 2025). A primary or metastatic malignant neoplasm involving the stomach. "The splicing factor PTBP3 promotes COX11 exon skipping, allowing gastric cancer organoids to evade cuproptosis." (PMID 40270362, 2025). "A shortened protein produced by PTBP3‐triggered exon skipping in COX11 allows cancer cells to evade cuprotosis in gastric cancer." (PMID 41399527, 2025). "In gastric cancer, circRNA‐mediated pathways drive expression of oncogenic RON variants, and PTBP3‐mediated skipping of COX11 exons facilitates resistance to cuproptosis." (PMID 41399527, 2025). "Antisense oligonucleotide drugs targeting PTBP3‐mediated COX11 alternative splicing, in combination with copper ionophores, promote cuproptosis in organoids, thereby providing a therapeutic approach for gastric cancer peritoneal metastasis." (PMID 40270362, 2025). "PTBP3-mediated exon 4 skipping in COX11 pre-mRNA is critical for tumor cell survival and progression in gastric cancer peritoneal metastasis, providing a potential therapeutic strategy targeting copper metabolism." (PMID 41158129, 2025). "To confirm whether COX11 undergoes exon skipping mediated by PTBP3, we first conducted agarose gel electrophoresis (AGE), which revealed two distinct transcripts—long and short forms—of the COX11 gene across various gastric cancer cell lines." (PMID 40270362, 2025). "Therefore, we propose that COX11 holds significant research value in facilitating the malignant progression of gastric tumors and the peritoneal metastasis of gastric cancer." (PMID 40270362, 2025). "These experimental results confirm that in the established animal model of peritoneal metastasis from gastric cancer cells, PTBP3 regulates COX11 alternative splicing, significantly impacting tumor metastatic progression." (PMID 40270362, 2025). "A correlation analysis between the percent splicing index (PSI) values of COX11 and PTBP3 protein expression levels was conducted on 20 gastric cancer peritoneal metastatic samples and 22 primary gastric cancer samples, revealing a significant correlation between these factors." (PMID 40270362, 2025).
mitochondrial encephalopathies (2 papers, 2023 to 2025). "Biallelic pathogenic variants in the COX11 protein were previously identified in two unrelated children with infantile-onset mitochondrial encephalopathies." (PMID 38068960, 2023). "Mutations in COX11, similar to mutations in the mitochondria Cu chaperones SCO1 and SCO2, are associated with an infantile-onset mitochondrial encephalopathy demonstrating the importance of COX11 for mitochondria function." (PMID 39172219, 2025).
colon carcinoma (1 paper, 2016). "Transcript‐level upregulation of SLC31A1,SCO1, and COX11 was also confirmed by the analysis of different colon carcinoma cell lines (Caco‐2, HT116, HT29) and cancer cell lines of different tissue origin (MCF7, PC3)." (PMID 27516958, 2016).
metastatic cancer (1 paper, 2025). A carcinoma which has spread from the original site of growth to another anatomic site. "In conclusion, our study identifies PTBP3 as a key regulator of COX11 alternative splicing and highlights its role in the accumulation of shorter transcripts in metastatic cancer lesions." (PMID 40270362, 2025).
mycoplasma pneumonia (1 paper, 2025). "Upregulation of miR-10a-3p was observed to downregulate COX11 and activate the NF-κB signaling pathway, promoting the progression of mycoplasma pneumonia." (PMID 38779731, 2025).
osteosarcoma (1 paper, 2023). A usually aggressive malignant bone-forming mesenchymal neoplasm, predominantly affecting adolescents and young adults. "Among them, FDX1, TOMM20 and NDUFB9 were associated with poor survival of osteosarcoma while COX11, MFN2 and ATP6V1E1 predicted good." (PMID 37405988, 2023). "A total of six cuproptosis-mitochondrion genes (FDX1, COX11, MFN2, TOMM20, NDUFB9 and ATP6V1E1) were identified to be associated with the prognosis of osteosarcoma." (PMID 37405988, 2023). "In this study, a total of six key cuproptosis-mitochondrion genes (FDX1, TOMM20, NDUFB9, COX11, MFN2 and ATP6V1E1) associated with prognosis of osteosarcoma were finally identified." (PMID 37405988, 2023). "The expression of FDX1, COX11, MFN2, TOMM20 and NDUFB9 at mRNA level was elevated in osteosarcoma cells compared with normal osteoblast hFOB1.19." (PMID 37405988, 2023). "Finally, it was experimentally verified that the expression of FDX1, COX11, MFN2, TOMM20 and NDUFB9 at mRNA levels was elevated in osteosarcoma." (PMID 37405988, 2023). "However, we are not aware of any study on the immunological aspects of FDX1, TOMM20, NDUFB9, COX11, MFN2 and ATP6V1E1 in osteosarcoma for the time being, which is a direction we need to study subsequently." (PMID 37405988, 2023).
Sepsis (1 paper, 2025). Sepsis is defined as life-threatening organ dysfunction caused by a dysregulated host response to infection. "The expression of SLC31A1, CD274, ATOX1, MTF1, UBE2D1, DLD, and VEGFA was found to be upregulated, while that of DLST, UBE2D2, COX11, DLAT, GLS, FDX1, and ULK2 were significantly downregulated in patients with sepsis-associated ALI." (PMID 38779731, 2025).
Spastic paraparesis (1 paper, 2025). Partial loss of the ability to move the lower limbs accompanied by spasticity of the lower limbs. "Specifically, disruptions were observed in mitochondrial dynamics and calcium homeostasis, alongside downregulation of key proteins like COX11, a copper chaperone for complex IV assembly, and NFU1, an iron-sulfur cluster protein linked to spastic paraparesis and infection-related worsening." (PMID 40051915, 2025).
cancer (5 papers, 2010 to 2023). A tumor composed of atypical neoplastic, often pleomorphic cells that invade other tissues. "In this sense, the significant correlations between CTR1 (SLC31A1 gene), SCO1, and COX11 mRNA levels suggest that such transcriptional upregulation might be part of a gene regulation program associated with cancer proliferation." (PMID 27516958, 2016). "In particular, a correlated upregulation of SLC31A1, SCO1, and COX11 mRNA has been observed in cancer cells in vivo and in culture conditions." (PMID 27516958, 2016). "We also found a strong causal association (OR per SD, 1.26; 95% CI: 1.15–1.37, PSMR = 2.94 × 10−5) between COX11 expression and luminal B-like/HER2-negative cancer." (PMID 36634566, 2023).
tumor (5 papers, 2022 to 2025). "In contrast, in tumor tissues, a significant decrease in COX11 expression was observed in samples with combined T2DM." (PMID 39901036, 2025). "Through lentiviral transfection, we achieved PTBP3 overexpression in these modified cells, allowing us to assess the impact of PTBP3 on COX11 splicing events and their implications for tumor biology." (PMID 40270362, 2025). "In the proteomic dataset, COX11 protein expression levels were found to be significantly higher in tumor samples from CRC patients." (PMID 39901036, 2025). "Overall, PTBP3‐mediated exon 4 skipping in COX11 pre‐mRNA is critical for tumor cell survival and progression in GCPM, offering potential therapeutic strategies targeting copper metabolism." (PMID 40270362, 2025). "In tumor tissues, a trend of increasing COX11 expression levels was observed in cells such as endothelial cells and macrophages." (PMID 39901036, 2025). "COX11 was the key gene for co-morbidities: in tumor tissues, COX11 expression was significantly higher than that in normal colon tissues." (PMID 39901036, 2025). "We discovered that COX11 expression levels, both in mRNA and protein, were slightly elevated in tumor tissues." (PMID 39901036, 2025). "In line with the expected trend, in the tumor tissues, we observed an increase in COX11 expression levels in cells such as endothelial cells and macrophages (although no statistical difference was observed)." (PMID 39901036, 2025). "Mechanistically, through full‐length transcriptome sequencing, PTBP3 mediates exon 4 skipping in its target gene COX11, leading to shorter transcripts that impair COX11 protein function, reducing mitochondrial copper content and enabling tumor cells to evade cuproptosis." (PMID 40270362, 2025). "Therefore, when COX11 expression levels were elevated in tumor tissues, we observed a better prognostic outcome in CRC patients." (PMID 39901036, 2025). "To explore the involvement of PTBP3 in modulating the alternative splicing of COX11 in vivo, we constructed MKN45 cells expressing luciferase, enabling the monitoring of changes in tumor behavior." (PMID 40270362, 2025). "In tumor tissues of T2DM-CRC patients, the proportion of M2 macrophages was significantly higher in the COX11 high-expression group." (PMID 39901036, 2025). "These recovery experiments collectively demonstrated that alterations in the long and short COX11 transcripts, mediated by PTBP3, significantly influence the invasion and proliferation of tumor cells and organoids." (PMID 40270362, 2025). "In tumor tissues from TCGA-COREAD patients, the COX11 high-expression group showed a significant drop in activated dendritic cells and a large rise in the number of M0 macrophages." (PMID 39901036, 2025). "In tumor tissues from patients with combined T2DM-CRC, there was a notable rise in the percentage of M2 macrophages in the COX11 high-expression group." (PMID 39901036, 2025). "The expression of COX11, COX17, LIAS, CDKN2A and AOC3 was significantly higher in tumor tissues than in normal tissues." (PMID 38078879, 2023). "In CRC tumor tissues, there was an increase in the mRNA expression level of COX11 in the external dataset, whereas in T2DM patients, there was a notable drop in the mRNA expression level of COX11." (PMID 39901036, 2025). "However, COX11 gene expression was significantly lower in patients with comorbidities than in patients without T2DM in tumor tissue." (PMID 39901036, 2025). "Meanwhile, we identified COX11 as a potential immune-related molecular marker closely related to T2DM-promoted CRC progression, and found that it might be closely related to macrophages in tumor tissues by immune infiltration and single-cell transcriptome analysis." (PMID 39901036, 2025).
mitochondrial disease (1 paper, 2023). "Based on the complete loss of COX function in the Y250* mutant, our data suggest that the p.T256Nfs*8 mutation in COX11 has a major contribution to the clinical symptoms associated with the mitochondrial disease in this patient." (PMID 38068960, 2023).
COX11 also shares sentences with these, for which no sentence is quoted: infection (3 papers); colorectal cancer (2); bladder tumors (1); breast tumour (1); encephalomyopathies (1); gastric tumors (1); migraine (1); polyposis (1); prostate carcinoma (1); renal fibrosis (1).